NANOG (Nanog homeobox)
Diseases named in the same sentence as NANOG in open-access papers (continued):
Sharing a sentence is not in itself a finding about the gene and the disease.
cancer (continued). "To further explore the relationship between FGFR1 signaling and cancer stem cell traits, we measured the mRNA levels of stem cells markers CD133, NANOG, OCT4 and SOX2, when FGFR1 signals were activated by bFGF, and in the presence of FGFR1 inhibitor." (PMID 26936993, 2016). "NANOG-expressing cancer cells manifest certain CSC properties and inducible NANOG expression, in a time-dependent manner, reprograms bulk cancer cells into a CSC phenotype." (PMID 27867534, 2016). "As expected, the addition of the siRNAs for cancer stem markers, si-OCT4 or si-NANOG, decreased the size and quantity of the clones and spheroids." (PMID 27056900, 2016). "On the other hand, genomic occupancy of NANOG in LNCaP cells differed from that of NANOG1 in ESCs, suggesting significant differences between NANOG in ESCs and in cancer cells." (PMID 27867534, 2016). "Our results showed that reprogramming factors such as OCT4, SOX2, NANOG, LIN28 and miR-302a were upregulated significantly in 3D-cultured cancer cells compared with their monolayer counterparts." (PMID 25883172, 2015). "As we have seen in other cancers and cancer cell lines, knockdown of DCLK1 reduced the expression of stem cell pluripotency factors MYC, NANOG, POU5F1/OCT4, and SOX2 in Caki-2 cells." (PMID 25605241, 2015). "On the other hand, stem cell markers such as OCT4, SOX2, NANOG and GATA4 and cancer stem cell (CSC)–like markers including ALDH1A1, CD44 and CD133 were not upregulated." (PMID 25875914, 2015). "RT-PCR analysis further revealed that cancer cells upregulate several CSC markers upon co-culture with ADSCs, including SOX2, NANOG, ALDH1A1, and ABCG2." (PMID 25797257, 2015). "Several miRNAs have been demonstrated to regulate stemness factors such as OCT4, NANOG, SOX2 and KLF4 in cancer cells, thereby modulating the proliferation, apoptosis, differentiation, drug resistance and immunity of cancer cells." (PMID 25603874, 2015). "ZNF671 re-expression in UC cell lines, via ectopic expression, inhibited tumor growth and invasion, in possible conjunction with downregulation of cancer stem cell markers (c-KIT, NANOG, OCT4)." (PMID 26320192, 2015). "DU145R80 show a cancer stem cell (CSC)-like signature with a high expression of CSC markers including CD44, CD133, NANOG, Snail, Oct4 and ALDH7A1 and CSC-related genes as STAT3." (PMID 26312765, 2015). "High expression of NANOG and OCT4 has been positively correlated with histologically high-grade carcinomas and clinically poor prognosis." (PMID 26626427, 2015). "The BORIS-positive cells isolated using BORIS-molecular beacon, expressed higher telomerase hTERT, stem cell (NANOG, OCT4, SOX2) and cancer stem cell marker genes (CD44 and ALDH1) compared to the BORIS-negative tumor cells." (PMID 25279549, 2014). "Cancer stem cell markers of SP cells, OCUM-12/SP and OCUM-2MD3/SP, such as CD44, CD133, and NANOG, were analyzed by RT-PCR." (PMID 25379943, 2014). "Association with cancer was used as a third criterion in gene selection, because many early development related genes, such as NANOG, OCT4, SOX2, DPPA5A and STELLAR are relevant for cancer." (PMID 25089626, 2014). "Positive reactions for NANOG and OCT4 were predominantly localized in the nuclei of cancer cells and the cell nuclei of PIN." (PMID 25120646, 2014). "The expression of NANOG, OCT4, Sox, NESTIN and CD44 has been observed in human prostate ADC cells, which suggests the importance of cancer stem and progenitor cells in prostate carcinogenesis." (PMID 25120646, 2014). "Previous studies have demonstrated the activation of downstream targets of NANOG, OCT4, SOX2 and MYC genes in aggressively growing human cancers." (PMID 24023739, 2013).
cancer (continued). "We examined the expression levels of CIC/CSC related markers including ALDH1, OCT4, NANOG, SOX2 and Caveolin-1 in the intralymphatic cancer cells to evaluate their relationship to lymph node metastasis." (PMID 24376714, 2013). "MCSCs possessed the high expression of cancer stem cell markers (CD133, CD44, OCT4, NANOG, and ABCG2) and the ability of differentiation." (PMID 24188098, 2013). "Among the regulatory genes involved in pluripotent maintenance of ESCs, NANOG was found to express a NANOGP8 retrogene locus in a wide variety of somatic and cancer cells." (PMID 23662114, 2013). "It was also shown that ectopic expression of HIFs in cancer cell lines can induce embryonic stem cell markers, like SOX2 and NANOG." (PMID 23451260, 2013). "We therefore investigated the CpG methylation pattern of NANOG (also known as NANOG1), OCT4, SOX2, KLF4 and c-MYC in human cancer cell lines by bisulfite sequencing approach." (PMID 24023739, 2013). "It has been demonstrated that OCT4, SOX2, c-MYC, LIN28, NANOG and KLF4 are required for ESC self-renewal and pluripotency and are upregulated in some aggressive cancers and in CSCs." (PMID 24040120, 2013). "We also found that short-term telomerase inhibition results in decreased expression of genes, such as OCT3/4, NANOG, SOX2, and BMI1, that regulate normal and cancer stem cells." (PMID 20824134, 2010). "Since NANOG is essential for maintaining the cancer stem cell (CSC)-like traits of colon cancer spheroids, TRRAP may promote cancer spheroid development." (PMID 41227365, 2025). "Androgen deprivation therapy promotes the expansion of cancer stem cells (CSCs) by altering the tumor microenvironment and upregulating key stem cell markers, including OCT4, SOX2, NANOG, CD133, and CD44, driving tumor initiation, progression, and recurrence in PCa." (PMID 40722714, 2025). "Crucial stemness genes such as KLF4, OCT-4, SOX2, NANOG, and C-MYC, which are important regulators of pluripotency and the capacity for self-renewal in CSCs, were expressed in cancer cells exposed to 5-FU in comparison to both spheroids and their parental population." (PMID 40251609, 2025). "Collectively, these findings suggest that PP1γ may regulate YAP1 dephosphorylation and promote the expression of cancer stem cell markers SOX2 and NANOG, thereby enhancing the tumorigenic potential of ESCC cells." (PMID 40626009, 2025). "Also, treatment with EC359 reduced the spheroid formation of EC cancer stem cells and reduced the levels of cancer stem cell markers SOX2, OCT4, and NANOG." (PMID 40804837, 2025). "In cervical cancer, acetyl-CoA, a metabolite of FAO, was shown to increase the acetylation of histone H3 on the promoters of stemness genes OCT4, SOX2, and NANOG, thereby further enhancing the cancer stemness and lymph node metastasis." (PMID 40647402, 2025). "Given that the GSC state is not a stable clonal subpopulation but rather a plastic state induced by the tumor microenvironment, we scored cells based on classic GSC markers (PROM1, SOX2, NES, OLIG2, BMI1, NANOG, POU5F1) and defined the top 2% of cancer cells with the highest stemness scores as GSCs." (PMID 41041071, 2025). "Moreover, FoxM1 can upregulate the expression of cancer stemness genes, such as BMI1, NANOG, and c-MYC, in HCC cells." (PMID 40050970, 2025). "Thus, we also examined expression levels of HNSCC specific cancer stem cell (CSC) markers, CD44 and ALDH, as well as other markers for HNSCC stemness, SOX2, NANOG, and BMI1." (PMID 38435825, 2024). "Furthermore, the high CBLL1 expression observed in the tumourspheres was accompanied by the upregulation of other established cancer stem cell markers, including LGR5, NANOG, SOX2, KLF4 and c-MYC mRNA levels." (PMID 38339195, 2024). "In addition to CD44, Nanog Homeobox (Nanog), SRY (Sex Determining Region Y)-Box 2 (SOX2), and Octamer-Binding Transcription Factor 4 (Oct4) play crucial roles in maintaining cancer stemness progression and the poor prognoses in cancer patients." (PMID 38612715, 2024).
cancer (continued). "Alone or in cooperation with other signalling pathways, NF-κB promotes the expression of a wide variety of downstream targets, including stem factors (NANOG, SOX2, CD44, and others) and microRNAs, like let-7 and microRNA-21, contributing to self-renewal and expansion features of cancer stem cells." (PMID 38612718, 2024). "In fact, studies indicate that HIF stimulates the expression of stem cell markers like OCT4, SOX2, NANOG, MYC, and miR-302 in cancer cells, implying that hypoxic niches may have a significant role in transforming non-cancer stem cells into cancer stem cells." (PMID 39201332, 2024). "Alu retrotransposons located in the NANOG and OCT4 promoters containing AhR binding sites are transcribed by RNA polymerase III, and they repressed NANOG and OCT4 expression in differentiated carcinoma cells." (PMID 38791215, 2024). "Specific surface markers of cancer stem cells, such as the stem cell marker Prominin-1 (CD133), Octamer-binding transcription factor 4 (OCT4), Transcription factor SOX-2 (SOX2), and Homeobox protein NANOG (NANOG), are frequently used for classifying cancer stem cells." (PMID 36769824, 2023). "Additionally, higher levels of NANOG and OCT4 have been correlated with advanced cancer stages and lower survival rates among patients in both OSCC and Pulmonary adenocarcinoma." (PMID 38170015, 2023). "Thus, it can be concluded that chemoresistant cells are characterized by the accumulation of cancer stem cells and the increased expression of stemness (CD44, CD133, CD10, ALDH) and pluripotency (NANOG, BMI1, OCT4, SOX2) markers." (PMID 37453969, 2023). "HCC patient specimens were stained for MSI2, MYC and NANOG to test if MSI2-mediated MYC translation is TIC-specific or if non-TIC bulk cancers also show a similar tendency." (PMID 37117191, 2023). "Phosphorylation of STAT3 resulted in the activation of the transcription factor NANOG, which is responsible for regulating the properties of the epithelial-mesenchymal transition (EMT), on the one hand, and maintaining the stemness of cancer stem cells (CSCs) on the other." (PMID 36835075, 2023). "To evaluate the kinetics of cancer stemness changes during the osteogenic and adipogenic inductions, we examined the relative gene expression of the OCT4, SOX2, and NANOG markers in the CD44+ cells at the beginning (0 days), and after 7, 14, and 21 days of differentiation." (PMID 36902135, 2023). "LC3B upregulation in NANOG promotes immune resistance through stimulating over-activation of EGFR signaling, and the NANOG-LC3B-EGFR axis is a key factor in controlling NANOG immune-refractory cancers as a central molecular target." (PMID 37422448, 2023). "Soft ECM (0.5 kPa) induces the reprogramming of H1299control cells to a cancer stem cell-like state and NANOG expression, but not in H1299RASSF1A cells." (PMID 37468874, 2023). "Together with NANOG and SOX2, OCT3/4 is widely regarded as marker of cancer stem cells, and higher expression of OCT3/4 has been proven to indicate worse clinical outcomes in most cancer types, i.e., more aggressive tumors, short overall survival and chemoresistance." (PMID 37476834, 2023). "Combined analysis of the results of differential expressions of the genes (11 lenvatinib target genes and NANOG) and the anti-proliferative effect indicated that the anti-cancer effect of lenvatinib on HCC was not dose dependent." (PMID 37894463, 2023). "NANOG and KLF4 are transcriptional factors regulating cancer stem cell phenotype." (PMID 37283789, 2023). "It modulates cancer stem cell stemness and pluripotency by targeting many embryonic transcriptional factors that enhance the oncogenic activity of metastatic cancers, including OCT4, SOX2, NanoG, and KLF4." (PMID 37513415, 2023). "The OCT 4, NANOG, SOX 2 are the transcription factors or genes that maintain stemness in embryonic stem cell and may play a key role in cancer stemness too." (PMID 37954619, 2023).
cancer (continued). "Based on the original concept of the embryonal origin of cancer, and thanks to the advent of scRNA-seq technology, we were able to identify a population of GBM cells with concurrent high levels of the core ESC pluripotency factors OCT4, SOX2, and NANOG." (PMID 35565200, 2022). "Since stemness markers determine self-renewing cell populations with CSC characteristics in various types of cancers, we next examined the effect of TWIST1 overexpression on the induction of stemness genes SALL4, OCT4, NANOG and SOX2 in KYSE-30 and YM-1 ESCC cells." (PMID 36474162, 2022). "An increase in the cancer stem cell markers ALDH1A1, SOX2, and NANOG were also observed by PCR." (PMID 35102251, 2022). "MACC1 is directly associated with the regulation of c-MET expression, subsequently inducing EMT via elevated HGF/c-MET signalling, but also of the pluripotency marker NANOG and the cell adhesion factor SPON2, both contributing to cancer progression and metastasis." (PMID 35597866, 2022). "In addition to NANOG, Twist1 and Bmi1 are important factors in the promotion of EMT and are positively correlated with poor prognosis in various cancers." (PMID 36114703, 2022). "Unfortunately, another study showed the opposite effect depending on cell characteristics, including induction of CD44, OCT-4 and NANOG on HNSC cancer stem cells but decreased proliferation of nonstem cancer cells." (PMID 35327549, 2022). "Previous publications already report the transcriptional regulation of cancer- and metastasis-related genes by MACC1 in CRC, like the hepatocyte growth factor receptor c-MET, the adhesion factor SPON2 and the stem-cell transcription factor NANOG." (PMID 35597866, 2022). "Beyond the embryonic transcription factors OCT4, NANOG, and putative miR-1305 interference, POLR3G expression is also regulated by MYC and sensitive to MYC disruption in cancers featuring MYC upregulation, including colon carcinoma and acute myeloid leukemia cell lines." (PMID 36710885, 2022). "Though POLR3G expression broadly correlates with MYC levels across all cancer types, whether and to what degree MYC activity overlaps OCT4, NANOG, and potentially other context-specific master transcription factors remain important questions." (PMID 36710885, 2022). "Notably, the BCSC phenotype is characterized by several core pluripotency factors, such as Nanog homeobox (NANOG), which is crucial for maintaining cancer stem cells." (PMID 35628623, 2022). "Moreover, pimavanserin also impaired the expression of several Gli1 downstream cancer stem cell markers, including Oct-4, SOX2 and NANOG, and suppressed the size and number of PANC1 tumorspheres." (PMID 34439102, 2021). "Since NANOG, SOX2 and KLF4 are essential for converting tumor cells into aggressive stem-like cells, an increase in the expression of these markers in our study after irradiation further supports the increased cancer stem cell population." (PMID 33419140, 2021). "NANOG and OCT4 are highly activated in a variety of stem cells including cancer stem cells." (PMID 33669204, 2021). "Moreover, we demonstrate that NANOG regulates CXCR4 expression and promotes cancer cell migration through the SDF1/CXCR4 pathway." (PMID 34638956, 2021). "NANOG and its pseudogene, NANOGP8, are expressed not only in human germ cell tumors but also in several human cancers, including colorectal cancer, seminoma and breast carcinoma, oral cavity carcinoma, ovary carcinoma, renal carcinoma, and malignant cervical epithelial cells." (PMID 35008480, 2021).
cancer (continued). "In cancer immunity and brain metastasis, lncRNA Xist involves cancer immunity in high expression programmed cell death protein 1 ligand TNBC cells via activating both OCT4 and NANOG though activating PI3K/AKT/mTOR signaling pathway." (PMID 34178980, 2021). "Increased NANOG and SOX2 stemness gene expression in cancer cells treated with CAF-conditioned media may lead to greater cisplatin resistance." (PMID 34760886, 2021). "Consequently, the targets of STAT3, including NANOG, c-Jun, c-Myc, and BCL-XL, which played important roles in stemness of cancer, were also upregulated in RALYL-overexpressing cells." (PMID 33750796, 2021). "Additionally, when IGF-1 function was blocked by miR-28-5p, the expressions of cancer stemness-related genes SOX2, OCT4, and NANOG were repressed." (PMID 33669204, 2021). "In addition, persistent cells seemed to be enriched for cancer stem cells (CSCs) or their progenitors, as revealed by increased tumour sphere formation and increased expression of CSC markers including NANOG and CD49f." (PMID 34203746, 2021). "In addition, CPZ was able to downregulate the expression of OCT 3/4, SOX2, NANOG, Nestin, OLIG2 and ALDH1A3, universal cancer stem cells genes for GBM." (PMID 33718225, 2021). "By subjecting glioma, hepatoma, and lung cancer cells to hypoxia, the induced expression of putative cancer stem cell markers (OCT4, NANOG, LIN-28A) and dedifferentiation could be observed." (PMID 33804114, 2021). "Several factors known to play a central role in embryonic stem cells and used in epigenetic reprogramming, such as pluripotency factors OCT4, NANOG, SOX2 and Klf4, have been reported to be expressed in subpopulations of cancer cells from different tumour types." (PMID 33453053, 2021). "In addition, IL-6 treatment induced IGF-1 secretion and IGF-1R expression in NANOG/OCT4-HCC cell lines in a dose-dependent manner, suggesting crosstalk between IL-6/STAT3 signaling and IGF/IGF-1R signaling in HCC cancer stem cells." (PMID 33669204, 2021). "More recently, NANOG (a master regulator of embryonic stem cell pluripotency found to be frequently aberrantly expressed in a variety of cancers, including laryngeal SCC) has been proposed as a predictor of cancer progression for LD." (PMID 33058010, 2021). "NANOGP8, a member of embryonic stemness gene family NANOG, exhibited specific differential sequences at higher frequency in exosomes originated from GBM cancer cells and prominin-1 containing (CD133+) cancer stem cells (CSCs) as compared to the normal neural stem cells (NSC)." (PMID 32092088, 2020). "Consistently, silencing of HSP90AA1 in P3 cells but not in P0 cells and NANOG up-regulated human cancer cells markedly reduced the levels of them." (PMID 31992715, 2020). "NANOG (NANOG1) has 11 pseudogenes, among which NANOGP4, P5, and P8 are expressed in cancer cells." (PMID 32197405, 2020). "By further confirmation using qRT-PCR, the transcription of the reprogramming factors (NANOG, OCT4, and SOX2) was enhanced by CENPW silencing in HCC cells, implying the possibility of reprogramming into cancer stem cells which characterized by inhibition of cell proliferation and metabolic changes." (PMID 32635817, 2020). "NANOGP8 is expressed in many cancers and its ability to substitute for NANOG in reprograming activity, prompted us to analyze the relative contribution of NANOG and NANOGP8 in STAT3-dependent upregulation of total NANOG during our reprogramming procedure." (PMID 32580970, 2020). "Cancer stem cells exhibit high expression of OCT4, NANOG and SOX2, which represent their markers." (PMID 32664372, 2020). "Compared with control xenograft tumors, the mRNA levels of cancer stemness-related genes, including ABCG2, BMI1, NANOG, KLF4, and OCT4 were increased and the protein expression of ABCG2, Oct4, Bmi-1, and CD44 were also increased in HBx-expressing xenograft tumors." (PMID 32168902, 2020).